ENSG00000199392
Synonyms: LOC124900408
Gene: Small nucleolar RNA gene on chromosome 18 (77,431,563 to 77,431,689, reverse strand). Ensembl gene ENSG00000199392.
Gene Ontology:
Biological process: RNA processing
Cellular component: nucleolus
Homologues: Paralogues in human: SNORA25 (82% identical), SNORA25B (81% identical).